FSCN1 (fascin actin-bundling protein 1)
Diseases named in the same sentence as FSCN1 in open-access papers (continued):
Sharing a sentence is not in itself a finding about the gene and the disease.
ovarian carcinoma (continued). "Another study also reported upregulated expression of FSCN1, cortactin, and EGFR in TMAs of four ovarian carcinomas (serous carcinoma, mucinous carcinoma, endometrioid adenocarcinoma, and clear cell carcinoma)." (PMID 34830909, 2021). "In conclusion, we found that 20(S)-Rg3 reversed EMT to inhibit ovarian cancer cells migration and invasion via antagonizing DNMT3A-mediated methylation of pre-miR-145 to promote inhibition of miR-145 on FSCN1." (PMID 28881818, 2017). "In sporadic ovarian cancers, SAM analysis identified up-regulation of e.g. SHC1, which is involved in protein tyrosine kinase activity, and FSCN1, which is related to protein binding (online resource 3)." (PMID 24848881, 2014). "In contrast, another investigation reported enhanced expression of FSCN1 in primary, borderline, and metastatic ovarian cancers compared with the normal ovarian tissues where no FSCN1 expression was observed." (PMID 34830909, 2021). "Furthermore, while FSCN1 expression was significantly upregulated in borderline and malignant ovarian tumors, there was no expression of FSCN1 in benign ovarian tumors." (PMID 34830909, 2021).
lung adenocarcinoma (10 papers, 2015 to 2025). A carcinoma that arises from the lung and is characterized by the presence of malignant glandular epithelial cells. "FSCN1-induced PTPRF-dependent tumor microenvironment inflammatory reprogramming promotes lung adenocarcinoma progression via regulating macrophagic glycolysis." (PMID 37604869, 2023). "Fascin actin-bundling protein 1 (FSCN1) is highly expressed in multiple tumors and is associated with the progression of CRC and lung adenocarcinoma, and poor prognosis in adrenocortical carcinoma." (PMID 36248886, 2022). "Moreover, the concurrent alteration of the FRA1 targets, AXL, CDK6, and FSCN1 correlated with worse prognosis in lung adenocarcinoma, low grade glioma, and clear cell renal cell carcinoma." (PMID 41286309, 2025). "Moreover, in lung adenocarcinoma, FSCN1 promotes tumor development through PI3K/AKT signaling." (PMID 37491232, 2023). "The same linc-ROR/miR-145 axis overexpressed the fascin-acting-bundling protein 1 (FSCN1) gene, known to increase cell motility and directly related to EMT in lung adenocarcinoma cell lines." (PMID 36827545, 2023). "In this research, samples of lung adenocarcinoma were interrogated with TME-related genes, among which high expression of PLK1, LDHA, FURIN, FSCN1, and RAB27B was correlated with poor OS, while high expression of MS4A1 was correlated with longer OS compared with the MS4A1 low expression." (PMID 37604869, 2023). "LincRNA ROR could also sponge miR-145 and then release the miR-145 target FSCN1, and further contribute to the acquisition of chemoresistance and EMT phenotypes of docetaxel-resistant lung adenocarcinoma cells." (PMID 28832500, 2017). "FSCN1 was highly expressed in lung squamous cell carcinoma (LUSC, P < 0.05) but not in lung adenocarcinoma (LUAD)." (PMID 38077434, 2023).
melanoma (10 papers, 2015 to 2025). A malignant, usually aggressive tumor composed of atypical, neoplastic melanocytes. "Analysis of the melanoma TCGA dataset revealed that concurrent alterations of AXL, CDK6, and FSCN1 correlate with poor outcomes of melanoma patients." (PMID 41286309, 2025). "The PTEN/AKT/mTORC1/FRA1 signaling axis we previously identified now extends to the regulation of AXL, CDK6, and FSCN1, suggesting that PTEN loss promotes melanoma metastasis partly through this mechanism." (PMID 41286309, 2025). "Comprehensive multi-omics integration revealed transcriptional target genes of FRA1, with AXL, CDK6, and FSCN1 exhibiting increased expression in melanoma metastasis and a significant correlation with poor patient outcomes." (PMID 41286309, 2025). "Consistent with our study, FSCN1 downregulation was shown to inhibit melanoma cell proliferation and to promote invasion." (PMID 35156321, 2022). "Moreover, silencing AXL, CDK6, or FSCN1 significantly reversed the stimulation of melanoma cell invasion by FRA1." (PMID 41286309, 2025). "Our study shows that mechanistically the miR‐143/‐145 cluster functions in melanoma cells through targeting the cytoskeletal regulator FSCN1, one of the best hits identified by our screening, confirming previous studies indicating that FSCN1 is a direct target of both mature miRNAs." (PMID 35156321, 2022). "To evaluate the influence of FSCN1 downregulation among the various cellular effects mediated by miR‐143‐3p and miR‐145‐5p, we then performed a loss‐of‐function experiment using FSCN1‐specific siRNAs in BRAF‐mutant parental melanoma cells." (PMID 35156321, 2022). "Finally, qPCR and Western blot analyses confirmed that FSCN1 was downregulated at both mRNA and protein levels upon miR‐143‐3p and miR‐145‐5p ectopic expression in various melanoma cells and in cells stably overexpressing the cluster." (PMID 35156321, 2022). "However, a complete characterization of FSCN1 functions in melanoma is still missing and some published studies are controversial." (PMID 35156321, 2022). "Using the opposite strategy, we then asked whether ectopic expression of FSCN1 was able to revert the mesenchymal‐like phenotype and restore drug sensitivity in BRAFi‐resistant melanoma cells." (PMID 35156321, 2022). "FSCN1 downregulation may thus be exploited by melanoma cells to generate lineage plasticity and revert to a poorly differentiated phenotype during drug adaptation." (PMID 35156321, 2022). "Particularly, it has been suggested that TLR4 may contribute to melanoma progression and migration and that FSCN1 promotes EMT events." (PMID 33916029, 2021). "FSCN1 knockout in the melanoma WM793 cell line inhibited melanoma stemness." (PMID 33614909, 2021). "Western blot indicated that FSCN1 protein levels were lower in undifferentiated mesenchymal resistant cells compared to parental cells, while on the contrary, they were elevated in M249R melanoma cells acquiring genetic resistance compared to parental cells (Fig EV4A)." (PMID 35156321, 2022). "Future studies will be important to determine if Fscn1 functions redundantly with other actin cross-linking proteins, adhesion molecules and guidance cues in development and cancer invasion and metastasis, including NC-derived cancers like melanoma and neuroblastoma." (PMID 25607881, 2015). "Furthermore, pharmacological inhibition of CDK6 and FSCN1, and to a lesser extent AXL, suppressed melanoma metastasis and prolonged overall survival." (PMID 41286309, 2025). "However, in melanoma, FSCN1 knockdown did not exhibit inhibitory effects on cell migration but enhanced cell invasion." (PMID 33614909, 2021). "MITF levels are higher in melanocytes than melanoma cells, inversely correlated with AXL and FSCN1, but FRA1 modulation did not alter MITF levels, consistent with RNA-seq and Cut&Run data showing no direct FRA1 regulation of MITF." (PMID 41286309, 2025). "Silencing CDK6 and FSCN1, but not AXL, significantly reduced melanoma cell proliferation." (PMID 41286309, 2025).
colon carcinoma (9 papers, 2009 to 2023). "However, to the best of our knowledge, no studies have been reported on the association of the binding of miR-145-5p to FSCN1 with colon cancer." (PMID 36960218, 2023). "The lncRNA PTOV1-AS2/miR-145-5p/FSCN1 axis requires further study to fully exploit its potential value in the diagnosis, treatment, and prognosis of colon cancer." (PMID 36960218, 2023). "The underlying mechanism of PTOV1-AS2 enhancing the proliferation of colon cancer was by “sponging” miR-145-5p to upregulate FSCN1." (PMID 36960218, 2023). "In this study, we aimed to investigate the effect of rs67085638 on the expression of CCAT1/miR‐24‐3p/FSCN1 and the response of colon cancer to the treatment of PTX." (PMID 33709519, 2021). "In this study, we investigated the effect of rs67085638 on the expression of CCAT1/miR‐24‐3p/FSCN1 and the response of colon cancer to the treatment of PTX." (PMID 33709519, 2021). "It was reported that FSCN1 transcriptional activity is controlled by the promoter region (−219/+114); in breast and colon cancer, CREB and aryl hydrocarbon receptors (AhRs) bind with the −219/+114 promoter region." (PMID 34830909, 2021). "PTOV1-AS2 promotes colon cancer progression by “sponging” miR-145-5p to upregulate FSCN1." (PMID 36960218, 2023). "The results of the qRT-PCR analysis showed that FSCN1 was highly expressed in colon cancer tissues." (PMID 36960218, 2023). "Several reports have identified a useful prognostic value of FSCN1 in colon cancer, and targeting FSCN1 may provide potential therapeutic opportunities for colon cancer." (PMID 36960218, 2023). "We also examined the effect of the PTOV1-AS2/miR-145-5p/FSCN1 axis on the biological functions of colon cancer cells using a colon cancer cell line model with silenced expression PTOV1-AS2 and simultaneous silencing of miR-145-5p or upregulated FSCN1 expression." (PMID 36960218, 2023). "Also, Western blot analysis validated the changes of FSCN1 protein expression in different groups of colon cancer cells." (PMID 33709519, 2021). "In mouse and zebrafish models, FSCN1 expression was found to induce colon tumor invasion." (PMID 34830909, 2021). "Furthermore, we investigated the effect of the PTOV1-AS2/miR-145-5p/FSCN1 axis on the biological function of colon cancer cells using an in vitro colon cancer cell model with reduced expression of PTOV1-AS2 and simultaneous transfection of a miR-145-5p inhibitor or FSCN1 vector." (PMID 36960218, 2023). "The results showed that silencing miR-145-5p or upregulating FSCN1 expression could partially restore the reduced cell proliferation, migration, and invasion caused by silencing the expression of PTOV1-AS2 in the two colon cancer cell lines." (PMID 36960218, 2023). "However, some studies do not support the hypothesis that the β-catenin-TCF pathway has a specific role in regulating FSCN1 transcriptional activity in human MDA-MB-435 cells or in fascin-positive human colon cancer cells." (PMID 33614909, 2021). "We also explored the interaction between lncRNA PTOV1-AS2 and miR-145-5p and its target gene FSCN1 in order to determine the prospective application of the lncRNA PTOV1-AS2/miR-145-5p/FSCN1 axis in the diagnosis and prognosis of colon cancer." (PMID 36960218, 2023). "In another report, the over-expressed miR-451 in colon cancer cells was found to inhibit AMPK to activate mTORC1, which mediates FSCN1 expression and cancer cell progression." (PMID 25026294, 2014). "In addition, miR-145-5p decreased the protein expression of its target gene FSCN1 and reduced the PTOV1-AS2-induced expression of FSCN1 in colon cancer cell lines." (PMID 36960218, 2023). "Chromatin immunoprecipitations for CREB, AhR or β-catenin from extracts from fascin-positive or -negative human colon carcinoma cells identified that CREB and AhR specifically associate with the −219/+114 region of the FSCN1 promoter in fascin-positive colon carcinoma cells." (PMID 19340314, 2009).
osteosarcoma (6 papers, 2016 to 2025). A usually aggressive malignant bone-forming mesenchymal neoplasm, predominantly affecting adolescents and young adults. "FSCN1, an actin-binding protein with important functions in cell motility and migration, has been found to play an important role in development of osteosarcoma and chondrosarcoma." (PMID 36508875, 2023). "Additionally, in severe combined immunodeficiency (SCID) mice, enhanced FSCN1 expression provoked lung metastasis in osteosarcoma cells." (PMID 34830909, 2021). "Moreover, in vitro data also demonstrated the role of FSCN1 in inducing cancer cell migration by promoting filopodia formation and epithelial-mesenchymal transition (EMT) in various cancer cells, including ovarian, oral, hypopharyngeal, osteosarcoma, and pancreatic cancer cells." (PMID 34830909, 2021).
pancreatic cancer (6 papers, 2019 to 2023). "FSCN1 is not expressed in most adult human epithelia, but high FSCN1 expression has been associated with increased mortality in breast, ovarian, colorectal and pancreatic carcinomas and metastasis." (PMID 37875732, 2023). "On the other hand, in hypopharyngeal and pancreatic cancers, HIF-1α was reported to induce the overexpression of FSCN1." (PMID 34830909, 2021). "Heterogeneous expression of FSCN1 also does not promote pancreatic cancer (MIA PaCa-2 cell line) cell proliferation." (PMID 33614909, 2021). "In pancreatic cancer, miR-133a could exert the anticarcinogenic activity by directly targeting FSCN1, conversely, inhibition of miR-133a by LncRNA XIST could upregulate EGFR expression to accelerate PNI of pancreatic cancer." (PMID 34187567, 2021).
adrenocortical carcinoma (5 papers, 2019 to 2025). "Some of these, such as VAV2 and FSCN1, have already been investigated as targeted therapies in adrenocortical carcinoma." (PMID 41226387, 2025). "In the previous reported, the higher-regulation of FSCN1 indicates worse prognosis for patients with renal cell carcinoma and adrenocortical carcinoma." (PMID 36085041, 2022). "In adrenocortical carcinoma, FSCN1 is required for SF-1/VAV2-driven cell invasion." (PMID 41226387, 2025). "In addition, recent findings suggest that FSCN1 may be a useful druggable target for controlling adrenocortical carcinoma, a rare disease." (PMID 37875732, 2023).
cervical cancer (5 papers, 2021 to 2025). A primary or metastatic malignant neoplasm involving the cervix. "Our study found that the FSCN1 gene is related to radiosensitivity and is associated with therapeutic efficacy and prognosis in cervical cancer and head and neck cancer patients with PIK3CA alterations." (PMID 34249689, 2021). "Thus, it is important to study the underlying mechanisms of FSCN1 functions in cervical cancer." (PMID 35178306, 2022). "Therefore, FSCN1 may be a biomarker in cervical cancer and head and neck cancer patients at a high risk of metastasis." (PMID 34249689, 2021). "In our study, data analysis from the TCGA database revealed that FSCN1 expression was significantly elevated in cervical cancer cases." (PMID 40227870, 2025). "Our study provides important cues for further study on the regulatory mechanism of FSCN1 in cervical cancer." (PMID 35178306, 2022). "Our results demonstrated that FSCN1 is not only an actin-binding protein but also a transcriptional regulator and an angiogenic factor in cervical cancer." (PMID 35178306, 2022). "Here, to further explore the regulated targets of FSCN1, we knocked down FSCN1 in HeLa cells isolated from cervical cancer tissue." (PMID 35178306, 2022). "Altogether, these results indicated that FSCN1 is not only an actin binding protein, but also a transcriptional regulator and an angiogenic factor in cervical cancer." (PMID 35178306, 2022). "In summary, our study showed that FSCN1 is overexpressed in cervical cancer tissue and that genome-wide FSCN1 knockdown regulates the expression of target genes in HeLa cells." (PMID 35178306, 2022). "Our study provides an important basis and data platform to further clarify the role of FSCN1 in mediating the metastasis of cervical cancer." (PMID 35178306, 2022). "Our results indicated that FSCN1 is overexpressed in cervical cancer tissue and negatively regulates the expression of HBP1 in HeLa cells." (PMID 35178306, 2022). "We first analyzed the expression of FSCN1 in cervical cancer samples from the TCGA database, which includes the gene expression profile (FPKM) of 306 cervical cancer tumor and 3 normal tissues." (PMID 35178306, 2022). "Then, we analyzed the correlations between the expression levels of FSCN1 and these genes in cervical cancer tissues from TCGA." (PMID 35178306, 2022). "FSCN1 expression levels were found to be negatively correlated with miR-145 expression levels in cervical cancer tissues, and overexpression of miR-145 or knockdown of FSCN1 dramatically inhibited the proliferation of HeLa cells." (PMID 35178306, 2022). "The results indicated that FSCN1 is a transcriptional repressor and promotes metastasis in cervical cancer." (PMID 35178306, 2022). "Next, we found that higher expression of the FSCN1 gene in cervical cancer and head and neck cancer patients with PIK3CA alterations was associated with poorer overall survival and radiotherapy response." (PMID 34249689, 2021). "In spite of the confirmed role of FSCN1 in several human carcinomas, there has been a limited number of investigations pertaining to the presence and role of FSCN1 in cervical cancers." (PMID 34830909, 2021). "Thus, our study provides important insights for further study on the regulatory mechanism of FSCN1 in cervical cancer." (PMID 35178306, 2022). "Additionally, the expression of FSCN1 was correlated with the prognosis of patients with cervical cancer." (PMID 35178306, 2022). "To verify whether FSCN1 was overexpressed in cervical cancer tissues, we detected the expression of FSCN1 in cervical cancer." (PMID 35178306, 2022). "FSCN1 has also been reported to be a marker of increased invasive potential in cervical cancers." (PMID 35178306, 2022). "In fact, a limited number of studies have reported the roles of FSCN1 in cervical cancer." (PMID 35178306, 2022). "Moreover, FSCN1 showed relatively high expression in samples of cervical cancer at different stages of development compared to normal tissues." (PMID 35178306, 2022).
cervical cancer (continued). "In addition, we found that FSCN1 gene expression was lower in patients with cervical cancer (P < 0.001) and head and neck tumors (P < 0.001) with PIK3CA alterations than in those in the wild-type group." (PMID 34249689, 2021). "In this study, the use of Src/Abl inhibitor in HPV-positive cervical cancer cell lines (SiHa and HeLa) was found to restore β-catenin accompanied by the downregulation of FSCN1 expression pattern, thus inhibiting cell invasion ability of these cancer cell lines." (PMID 34830909, 2021). "However, the functions of FSCN1 in cervical cancers are still not fully understood." (PMID 35178306, 2022). "However, the functions of FSCN1 are still not fully understood in cervical cancers." (PMID 35178306, 2022). "In particular, the genome-wide regulated target genes of FSCN1 in cervical cancer remain unclear." (PMID 35178306, 2022). "However, the functions of FSCN1 in cervical cancer are still not fully understood." (PMID 35178306, 2022). "In addition, in our laboratory, we found FSCN1 to be overexpressed in cervical cancer tissue." (PMID 34830909, 2021). "Thus, FSCN1 might be a potential prognostic factor in cervical cancer." (PMID 35178306, 2022). "Therefore, further study should be conducted to reveal the molecular mechanism by which FSCN1 regulates the expression of HBP1 and ANGPTL4 in cervical cancer." (PMID 35178306, 2022). "Furthermore, using bioinformatics analysis in cervical cancer and head and neck cancer patients with PIK3CA alterations, FSCN1-co-expressed genes were enriched in the apoptosis pathway." (PMID 34249689, 2021). "FSCN1 may be a synthetic lethality gene with PIK3CA and its expression level may serve as a biomarker for prognosis and radiotherapy response in cervical cancer and head and neck cancer." (PMID 34249689, 2021). "Thus, FSCN1 negatively regulates four transcription factors (HLTF, HBP1, ZNF664, DDX17) and positively regulates ANGPTL4 (an angiogenic factor) and EPHA2 in both HeLa cells and cervical cancer tissues." (PMID 35178306, 2022). "The results showed that the expression of FSCN1 had a significant negative correlation (P < 0.05) with that of HLTF, HBP1, ZNF664, CTGF, DDX17, and KRT18 in cervical cancer tissues." (PMID 35178306, 2022).